LAYN (layilin)
Diseases named in the same sentence as LAYN in open-access papers (continued):
Sharing a sentence is not in itself a finding about the gene and the disease.
dementia (2 papers, 2018 to 2026). Loss of intellectual abilities interfering with an individual's social and occupational functions. "Using delirium in the dementia-free UKB GWAS as outcome, ADAM8, CCL25, PILRA and LAYN lost their MR causal effect significance (FDR q > 0.05)." (PMID 41286463, 2026). "We identified altered proteins in AD not common to other dementias like the E3 ubiquitin-protein ligase TOPORS, Layilin and MICB, and validated the association to AD of the previously controverted proteins DDIT3 and the E3 ubiquitin-protein ligase XIAP." (PMID 29541381, 2018).
gastric adenocarcinoma (2 papers, 2019 to 2021). "Additionally, LAYN expression was positively correlated with the infiltration of CD4+T and CD8+T cells, macrophages, neutrophils, and dendritic cells in colon and gastric adenocarcinomas." (PMID 34098960, 2021). "LAYN expression was positively correlated with infiltrating levels of CD4+ T and CD8+ T cells, macrophages, neutrophils, and dendritic cells (DCs) in colon adenocarcinoma (COAD) and stomach adenocarcinoma (STAD)." (PMID 30761122, 2019).
kidney cancer (2 papers, 2022 to 2025). Primary or metastatic malignant neoplasm involving the kidney. "Additionally, LAG3 CNV was associated with poor survival in PCPG and KICH; CXCL13 in kidney cancers (KIRC and KIRP) and MESO; LAYN in KIRP, SARC and LGG." (PMID 40076932, 2025).
Mycoplasma pneumoniae pneumonia (2 papers, 2022 to 2024). Interstitial pneumonia caused by extensive infection of the lungs (lung) and bronchi, particularly the lower lobes of the lungs, by mycoplasma pneumoniae in humans. "It is recognized in the literature that Mycoplasma pneumoniae pneumonia coincident with plastic bronchitis correlates with modulated expression of inflammatory proteins such as MUC5AC, MUC5B, and layilin." (PMID 38930514, 2024). "We utilized a protein chip to screen for significantly different proteins among the groups of healthy, general Mycoplasma pneumoniae pneumonia (GMPP) and refractory Mycoplasma pneumoniae pneumonia (RMPP) patients, where layilin exhibited a potent change across biology information technology." (PMID 35770160, 2022).
ovarian carcinoma (2 papers, 2019 to 2024). A malignant neoplasm originating from the surface ovarian epithelium. "In three datasets of PrognoScan, high LAYN expression levels can be used as an independent risk factor for poor prognosis in colorectal and ovarian cancers." (PMID 30761122, 2019). "Nevertheless, in these databases we found consistent prognostic correlations between LAYN expression in colon, gastric and ovarian cancers." (PMID 30761122, 2019). "Together these findings strongly suggest that LAYN is a prognostic biomarker in colorectal, gastric, and ovarian cancer." (PMID 30761122, 2019). "Furthermore, anaylsis of data from PrognoScan and Kaplan-Meier Plotter showed high level of LAYN expression was correlated with poor prognosis in colorectal, gastric and ovarian cancers." (PMID 30761122, 2019). "Notably, LAYN expression significantly impacts prognosis in 4 type cancers, including colorectal, breast, eye and ovarian cancers." (PMID 30761122, 2019). "Kaplan-Meier Plotter also showed a high LAYN expression correlated with high hazard ratio (HR) for poor overall survival (OS) and progress free survival (PFS) of gastric and ovarian cancers." (PMID 30761122, 2019).
psoriasis (2 papers, 2022 to 2025). An autoimmune condition characterized by red, well-delineated plaques with silvery scales that are usually on the extensor surfaces and scalp. "There were no changes in the relative expression of LAYN per cell when comparing Treg clusters from psoriasis skin with healthy control skin, suggesting that LAYN expression is not increased on Tregs in inflamed skin." (PMID 40690378, 2025). "In addition to the cytokines noted above such as IL17F (0.967), and CXCL13 (0.325), this set contained identified psoriasis-specific genes with less established functional roles, such as ARHGEF12 (0.303), ENTPD1 (0.628), LAYN (0.122) and HAVCR2 (0.560)." (PMID 35958578, 2022).
thyroid cancer (2 papers, 2019 to 2024). "Meanwhile, high LAYN expression was correlated with better prognosis of DFS in KIRP and THCA (thyroid carcinoma) as well as OS in SKCM (skin cutaneous melanoma)." (PMID 30761122, 2019).
Autoimmunity (1 paper, 2021). The occurrence of an immune reaction against the organism's own cells or tissues. "CD8+ T cells expressing high levels of IL-17 (Tc17 cells) infiltrating psoriatic lesions are also enriched for layilin expression compared with T cells from healthy skin, suggesting that although layilin may protect against cancer, it could contribute to autoimmunity." (PMID 35024681, 2021).
breast tumor (1 paper, 2017). "KANSL1 has also been reported fused with ORMDL3 and LAYN in one breast tumor and with UNC45B in one lung tumor." (PMID 28423358, 2017).
diabetes (1 paper, 2025). "In a group of the Korean population, CDH3 (cadherin-3), JAM-B, LAYN (layilin), and SCARA5 (scavenger receptor class a member 5) were also found to be positively associated with DSP in patients with diabetes." (PMID 40002826, 2025).
glioblastoma multiforme (1 paper, 2019). "High LAYN expression levels were associated with poorer prognosis of OS and DFS in COAD, OV (ovarian serous cystadenocarcinoma), and UVM (uveal melanoma); DFS in GBM (glioblastoma multiforme) and OS in HNSC, MESO (mesothelioma) and STAD." (PMID 30761122, 2019).
Hyperglycemia (1 paper, 2025). An increased concentration of glucose in the blood. "Similarly, in human intestinal organoids, HA35 counteracts hyperglycemia-induced barrier disruption by preserving zonula occludens-1 (ZO-1) and occludin localization through the HA receptor, layilin." (PMID 41305610, 2025).
inflammatory bowel disease (1 paper, 2022). A spectrum of small and large bowel inflammatory diseases of unknown etiology. "LAYN was also involved in the epithelial-mesenchymal transition (EMT) of renal tubular epithelial cells induced by tumor necrosis factor-α (TNF-α), and played a key role in the tight junctions of the intestinal epithelium induced by HA35 in inflammatory bowel disease." (PMID 36260222, 2022).
inflammatory skin disease (1 paper, 2025). Inflammatory skin disorders covers a broad category that includes many conditions ranging in severity, from mild itching to grave medical health complications These disorders are common in people of all ages and races. "Here, we interrogate the functional biology of Treg expression of layilin in inflammatory skin disease." (PMID 40690378, 2025).
lung squamous cell carcinoma (1 paper, 2019). "We analyzed the correlations between LAYN expression and immune marker genes of different immune cells, included CD8+ T cells, T cells (general), B cells, monocytes, TAMs, M1 and M2 macrophages, neutrophils, NK cells and DCs in COAD and STAD, using lung squamous cell carcinoma (LUSC) as the control." (PMID 30761122, 2019).
pancreatic cancers (1 paper, 2019). "This analysis revealed that the LAYN expression was higher in breast, colorectal, gastric, kidney, pancreatic cancers, and lymphoma tumors compared to the normal tissues." (PMID 30761122, 2019).
renal carcinoma (1 paper, 2025). A carcinoma arising from the epithelium of the renal parenchyma or the renal pelvis. "Tumor necrosis factor-alpha (TNF-α) upregulates layilin expression in both chondrocytes and human renal carcinoma cells, whereas TGF-β lacks this effect in renal carcinoma cells." (PMID 41404063, 2025).
rheumatoid arthritis (1 paper, 2022). A chronic, systemic autoimmune disorder characterized by inflammation in the synovial membranes and articular surfaces. "Previous research had demonstrated secretion of inflammatory factors from chondrocytes by layilin signaling in rheumatoid arthritis (RA), they also found that TNF-α upregulated expression levels of layilin in the chondrocytes." (PMID 35770160, 2022). "Layilin signaling could regulate inflammatory factors in rheumatoid arthritis." (PMID 35770160, 2022). "Furthermore, layilin is speculated to exacerbate inflammation in rheumatoid arthritis (RA)." (PMID 35770160, 2022).
systemic lupus erythematosus (1 paper, 2025). An autoimmune multi-organ disease typically associated with vasculopathy and autoantibody production. "Emerging evidence also links layilin to systemic lupus erythematosus (SLE)." (PMID 41404063, 2025).
tumor (59 papers, 2011 to 2025). "Layilin, a transmembrane protein implicated in immune evasion, can potentiate T cell exhaustion and suppress the anti-tumor immune function of CD8 + T cells upon upregulation." (PMID 41395459, 2025). "Our data uncovered the close association between LAYN expression and the vast majority of tumor-infiltrating immune cells as well as diverse immune cell markers." (PMID 36398067, 2022). "LAYN might contribute to tumorigenesis via its positive correlation with immune checkpoint molecules and tumor-associated macrophages (TAMs)." (PMID 38430385, 2024). "However, the underlying functions and mechanisms of LAYN in tumor progression and tumor immunology is still unclear." (PMID 30761122, 2019). "Collectively, these findings suggest that layilin is a multifunctional regulator of tumor immunity and progression, and its effects are likely dependent on cellular context, tumor type, and TME." (PMID 41404063, 2025). "For instance, layilin, a membrane glycoprotein expressed by certain tumor-specific CTLs, enhances LFA-1 activation by stabilizing its interaction with ICAM-1." (PMID 39911389, 2025). "In tumor cells, layilin promotes malignant glioma invasion through snail family transcriptional repressor 1 (SNAI1), which suppresses nuclear metastasis associated 1 family member 3 (MTA3), while also inhibiting low-density lipoprotein (LDL) uptake." (PMID 41404063, 2025). "Within the TME, layilin drives colorectal cancer metastasis and CCL20 secretion via the NF-κB signaling pathway to recruit tumor-associated macrophages (TAMs)." (PMID 41404063, 2025). "We have previously shown that layilin acts to anchor Tregs in tissues and that deletion selectively in these cells results in enhanced tumor growth." (PMID 40690378, 2025). "Emerging evidence highlights the multifaceted roles of layilin in oncology, influencing both tumor-intrinsic mechanisms and the TME." (PMID 41404063, 2025). "LAYN is reportedly highly expressed on tumor-infiltrating Tregs and mediates adhesion of Tregs in the skin." (PMID 38341270, 2024). "The LAYN protein plays an important role in cell adhesion, migration, and cooperates with the body’s anti-tumor immunity." (PMID 38430385, 2024). "Kyoto encyclopedia of genes and genomes (KEGG) enrichment analysis suggested that LAYN potentially influenced tumor progression through HPV infection and other cancer-related pathways." (PMID 38430385, 2024). "We employed TIMER database to investigate the variances of LAYN mRNA expression levels between tumor and normal tissues in a wide range of cancer types." (PMID 38430385, 2024). "We first explored the discordant expression of LAYN in pan-cancer tissues compared to their respective paracancerous tissues based on TCGA dataset, the results suggested the different tumor-specific roles of LAYN in different tumor types." (PMID 38430385, 2024). "During further exploration of the role of LAYN in tumor immunity and its potential as an immunotherapeutic target, we analyzed the correlation between LAYN and 57 common immune marker sets." (PMID 38430385, 2024). "LAYN expression potentially contributed to the suppressive function of tumor-infiltrating exhausted CD8+T cells and Tregs." (PMID 37024870, 2023). "LMW-HA induces the secretion of inflammatory factors, matrix hydrolases and pro-angiogenic factors by activating the specific receptors such as TLR2, TLR4, and LAYN of tumor cells, which dominates in the field of metastasis and colonization." (PMID 36698043, 2023). "In the present study, we found the elevated expression level of LAYN in the primary cancer patients than that of healthy controls regarding sample type, age, gender, tumor grade, cancer stage, nodal metastasis status, and histological subtypes." (PMID 36398067, 2022). "The number of tumor-infiltrating CD8+T cells was reduced and the expression of LAYN was down-regulated in tumor-infiltrating CD8+T cells in the low-dose anti-VEGFR2 combination group." (PMID 36260222, 2022).
tumor (continued). "To detect the expression of LAYN in the tumor tissues of LUAD patients, we collected clinic samples and performed flow cytometry, immunohistochemistry, and immunofluorescence." (PMID 36260222, 2022). "Low-dose anti-VEGFR2 antibody combined with anti-PD1 antibody therapy promoted anti-tumor immunity and the downregulation of LAYN in tumor-infiltrating CD8+T cells played an important role in this process." (PMID 36260222, 2022). "At the same time, the MFI of LAYN on tumor-infiltrating exhausted CD8+T (TIM3+PD1+CD8+T) was significantly higher in tumor tissues than that in para-tumor tissues." (PMID 36260222, 2022). "Layilin (LAYN) is a signature gene for tumor-specific Tregs and exhausted CD8+ T cells, and LAYN overexpression in CD8+ T cells suppressed the production of IFN-γ, suggesting that LAYN had an inhibitory effect on CD8+ T cells." (PMID 36119533, 2022). "In conclusion, the present study provided a perspective on the oncogenic roles of LAYN via regulating tumor immune cell infiltration in LIHC." (PMID 36398067, 2022). "In conclusion, LAYN was highly expressed on tumor-infiltrating CD8+T cells in tumor tissues of patients with LUAD." (PMID 36260222, 2022). "Previous studies had found that LAYN was a key gene involved in tumor-infiltrating lymphocytes of liver cancer." (PMID 36260222, 2022). "Several studies have also revealed the association of LAYN, CTLA4, and GZMK expression with tumor-infiltrating exhausted CD8+ T cells and a poor prognosis." (PMID 35854246, 2022). "The RNA-seq normalized expression values were used to compute the ratios of LAYN to GZMA and LAYN to IFNG for each tumor sample." (PMID 35197510, 2022). "To further study its internal mechanism, we analyzed the expression and function of LAYN on tumor-infiltrating CD8+T cells in tumor tissues after treatment." (PMID 36260222, 2022). "A previous study further found the LAYN is a crucial gene involved in liver cancer tumor-infiltrating lymphocytes." (PMID 30761122, 2019). "Analysis of the TCGA database revealed that increased LAYN expression correlated with poor prognosis in most tumor types (COAD, HNSC, MESO, OV, STAD, and UVM)." (PMID 30761122, 2019). "The results show that LAYN expression has significant correlations with tumor purity in 26 types of cancer and significant correlations with B cell infiltration levels in 14 types of cancers." (PMID 30761122, 2019). "Furthermore, LAYN plays a role in cancer development and enhances anti‐tumor immunity by promoting the activation of integrins." (PMID 38573314, 2024). "Further studies need to be conducted to determine whether LAYN is a crucial factor that mediates the M2 polarization of macrophages and ultimately results in tumor metastasis." (PMID 38430385, 2024). "Our findings might provide novel insights into the role of LAYN in HPV-related HNSCC, and expand the understanding of the underlying mechanism between LAYN and tumor-immune interactions." (PMID 38430385, 2024). "In order to further explore the role of LAYN in the tumor immune process and its potential as a target for immunotherapy, we analyzed the correlation between LAYN expression and various immune marker sets of immune cells in HPV-related HNSCC through GEPIA database." (PMID 38430385, 2024). "In a human tissue lymphocyte transcriptional atlas, analyzing RNA-SEQ data from colorectal and NSCLC tumors along with normal colon and lung samples, high expression of Tregs’ cellular signature genes, such as LAYN, MAGEH1 and CCR8, in whole tumor samples was associated with poor prognosis." (PMID 37901223, 2023). "They showed that LAYN was preferentially upregulated in tumor‐infiltrated FOXP3+Helios+ Tregs." (PMID 35474948, 2022). "Moreover, gene set enrichment analysis (GSEA) revealed that LAYN and its coexpressed genes primarily participated in immune response pathways, and LAYN expression was found significantly correlated with tumor immune cell infiltration in LIHC tissues." (PMID 36398067, 2022).